TRIM60 (tripartite motif containing 60)
Description:
E3 SUMO-protein ligase that mediates SUMOylation of TAB2 leading to inhibition of NF-kappa-B and MAPK pathways by suppressing the TRAF6/TAB2/TAK1 complex.
Synonyms: RNF129; RNF33; FLJ35882
Tractability: No criterion of Open Targets' tractability assessment is met for any kind of drug.
Gene: Protein-coding gene on chromosome 4 (165,016,458 to 165,041,749, forward strand). Ensembl gene ENSG00000176979.
Subcellular location (Human Protein Atlas): Nucleoli; Cytosol; Nucleoplasm
Gene Ontology:
Molecular function: protein binding; SUMO-ubiquitin ligase activity; ubiquitin protein ligase activity; zinc ion binding
Biological process: negative regulation of non-canonical NF-kappaB signal transduction; innate immune response; regulation of gene expression
Cellular component: cytoplasm
Genetic constraint (gnomAD): Loss-of-function variants: 0 observed, 0.26 expected, observed/expected ratio (o/e) 0, 90% interval 0 to 1.87. That is too few expected variants to judge how well the gene tolerates losing a copy. Missense variants: 523 observed, 567.77 expected, observed/expected ratio (o/e) 0.92, 90% interval 0.86 to 0.99. Synonymous variants: 187 observed, 206.7 expected, observed/expected ratio (o/e) 0.9, 90% interval 0.8 to 1.02.
Homologues: Orthologues: chimpanzee TRIM60 (98% identical), macaque TRIM60 (94% identical), rabbit TRIM60 (72% identical), mouse Trim60 (52% identical). Paralogues in human: TRIM61 (64% identical), TRIM75 (46% identical), TRIM39 (34% identical), TRIM68 (33% identical), TRIM38 (31% identical), TRIM6 (31% identical), TRIM41 (30% identical), TRIM21 (29% identical), TRIM34 (29% identical), TRIM5 (29% identical), TRIM11 (29% identical), TRIM22 (29% identical), and 68 more.
Diseases named in the same sentence as TRIM60 in open-access papers:
TRIM60 is named in the same sentence as 1 disease in open-access papers, as found by Europe PMC text mining. Sharing a sentence is not in itself a finding about the gene and the disease.
TRIM60 shares sentences with these, for which no sentence is quoted: ovarian tumors (1 paper).